BET1 (Bet1 golgi vesicular membrane trafficking protein)
Description:
Required for vesicular transport from the ER to the Golgi complex. Functions as a SNARE involved in the docking process of ER-derived vesicles with the cis-Golgi membrane (By similarity).
Synonyms: hBET1; MDRP
Tractability: Antibody: UniProt predicts a signal peptide or a membrane-spanning region. PROTAC: ubiquitination databases record sites on it; its protein half-life has been measured.
Gene: Protein-coding gene on chromosome 7 (93,962,762 to 94,004,382, reverse strand). Ensembl gene ENSG00000105829.
Subcellular location: Endoplasmic reticulum membrane; Golgi apparatus, cis-Golgi network membrane; Golgi apparatus membrane
Pathways (Reactome):
Vesicle-mediated transport: COPI-mediated anterograde transport; COPII-mediated vesicle transport
Gene Ontology:
Molecular function: protein binding; SNAP receptor activity
Biological process: endoplasmic reticulum to Golgi vesicle-mediated transport; vesicle fusion with Golgi apparatus; vesicle-mediated transport
Cellular component: cis-Golgi network; endoplasmic reticulum; endoplasmic reticulum membrane; membrane; endoplasmic reticulum-Golgi intermediate compartment membrane; Golgi membrane; SNARE complex; transport vesicle; Golgi apparatus
Genetic constraint (gnomAD): Loss-of-function variants: 8 observed, 9.18 expected, observed/expected ratio (o/e) 0.87, 90% interval 0.51 to 1.55. That is too few expected variants to judge how well the gene tolerates losing a copy. Missense variants: 110 observed, 118.7 expected, observed/expected ratio (o/e) 0.93, 90% interval 0.79 to 1.09. Synonymous variants: 34 observed, 42.43 expected, observed/expected ratio (o/e) 0.8, 90% interval 0.61 to 1.07.
Homologues: Orthologues: chimpanzee BET1 (100% identical), guinea pig BET1 (96% identical), macaque BET1 (96% identical), dog BET1 (95% identical), pig BET1 (94% identical), rabbit BET1 (92% identical).
Diseases named in the same sentence as BET1 in open-access papers:
BET1 is named in the same sentence as 30 diseases in open-access papers, as found by Europe PMC text mining. Sharing a sentence is not in itself a finding about the gene and the disease. The quoted sentences say what the papers report.
congenital muscular dystrophy (2 papers, 2021 to 2022). A muscular dystrophy that is characterized by diminished muscle tone (hypotonia), progressive muscle weakness and degeneration (atrophy), abnormally fixed joints, spinal rigidity, and delays in reaching motor milestones such as sitting or standing unassisted. "The first is Bet1 Golgi vesicular membrane trafficking protein (BET1), where low BET1 protein levels are associated with impaired ER-to-Golgi transport in congenital muscular dystrophy." (PMID 35627314, 2022). "This study describes three individuals with a progressive early‐onset congenital muscular dystrophy, and additional epilepsy in one, caused by biallelic variants in the BET1 gene." (PMID 34779586, 2021). "Here, we report three individuals, from two families, with severe congenital muscular dystrophy (CMD) and biallelic variants in BET1 (P1 p.(Asp68His)/p.(Ala45Valfs*2); P2 and P3 homozygous p.(Ile51Ser))." (PMID 34779586, 2021).
epilepsy (2 papers, 2021 to 2024). A brain disorder characterized by episodes of abnormally increased neuronal discharge resulting in transient episodes of sensory or motor neurological dysfunction, or psychic dysfunction. "We report detailed clinical data on three individuals of two independent families with biallelic variants in BET1, clinically manifesting as a severe and progressive early‐onset dystrophy with epilepsy in one patient." (PMID 34779586, 2021). "BET1 is involved in the vesicular transport from the ER to the Golgi complex and bi‐allelic variants establish impaired vesicular transport leading to muscular dystrophy complicated by epilepsy." (PMID 38652110, 2024). "We thus confirm the emerging role of ER‐to‐Golgi Q‐SNARE‐mediated transport in muscle homeostasis and disease and establish BET1 as a novel gene for CMD/epilepsy." (PMID 34779586, 2021). "Taken together, we establish BET1 as a novel CMD/epilepsy gene and confirm the emerging role of ER‐to‐Golgi Q‐SNARE gene variants in CMD with epilepsy." (PMID 34779586, 2021). "Thus, we establish BET1 as a novel CMD/epilepsy gene and confirm the emerging role of ER/Golgi SNAREs in CMD." (PMID 34779586, 2021). "Considering BET1 variants in individuals with epilepsy and/or CMD of unknown genetic origin may identify more individuals and thus provide further insight into the clinical manifestations and pathomechanism of BET1‐related disease." (PMID 34779586, 2021).
glioblastoma (2 papers, 2020 to 2023). The most malignant astrocytic tumor (WHO grade IV). "There is a report that BET1 was identified as part of a gene expression signature associated with a favorable prognosis in glioblastoma." (PMID 33552133, 2020). "In addition, BET1 is also associated with better prognosis in glioblastoma." (PMID 36979661, 2023).
muscular dystrophy (2 papers, 2021 to 2024). Muscular dystrophy (MD) refers to a group of more than 30 genetic diseases characterized by progressive weakness and degeneration of the skeletal muscles that control movement. "However, the full extent of muscular dystrophy and brain involvement in individuals with BET1 variants may be related to additional, cell‐specific alterations in protein trafficking that remain to be elucidated." (PMID 34779586, 2021).
acute myocardial infarction (1 paper, 2021). Necrosis of the myocardium, as a result of interruption of the blood supply to the area. "Both ET-1 and BET-1 may improve risk stratification of acute myocardial infarction and heart failure, and help predict outcomes post-HTx." (PMID 34950993, 2021).
Alzheimer disease (1 paper, 2021). A progressive, neurodegenerative disease characterized by loss of function and death of nerve cells in several areas of the brain leading to loss of cognitive function such as memory and language. "For example, Ubiquilin 1 (UBQLN1) expression is associated with neuronal loss seen in Alzheimer’s disease, which is of interest as cognitive decline was observed in at least one patient with BET1‐related disease." (PMID 34779586, 2021).
amyotrophic lateral sclerosis (1 paper, 2024). Amyotrophic lateral sclerosis (ALS) is a neurodegenerative disease characterized by progressive muscular paralysis reflecting degeneration of motor neurons in the primary motor cortex, corticospinal tracts, brainstem and spinal cord. "However, further studies—ideally on cohorts with defined genetic defects such as Charcot–Marie–Tooth neuropathies and hereditary forms of amyotrophic lateral sclerosis—are needed to elucidate the varying impact of BET1 in the formation of neurogenic targets more precisely." (PMID 38652110, 2024).
cholangiocarcinoma (1 paper, 2021). A carcinoma that arises from the intrahepatic biliary tree (intrahepatic cholangiocarcinoma) or from the junction, or adjacent to the junction, of the right and left hepatic ducts (hilar cholangiocarcinoma). "In conclusion, the results of the present study suggest that the cholangiocarcinoma (CHOL)-hub genes (SNX15, ATP2A1, PDCD10, BET1, and HMGA2) can be used as biomarkers of tumor progression, metastasis, therapy outcome, and poor prognoses of CHOL." (PMID 34831096, 2021).
congestive heart failure (1 paper, 2022). Failure of the heart to pump a sufficient amount of blood to meet the needs of the body tissues, resulting in tissue congestion and edema. "Thus, BPC 157 therapy as applied as intragastric application, per-oral in drinking water, might exert the reversal of the doxorubicin-induced congestive heart failure, effective even in the advanced status of failing heart in rats and mice studied by the reversal of the BET-1 plasma level." (PMID 36359218, 2022).
dystroglycanopathies (1 paper, 2021). "The data from individuals with BET1‐related disease further confirm that impaired SNARE‐mediated Golgi trafficking of α‐dystroglycan may contribute to this severe phenotype and highlights its relationship to α‐DG‐related CMD with CNS involvement (i.e., IDT‐related dystroglycanopathies)." (PMID 34779586, 2021).
Fanconi anemia (1 paper, 2023). Fanconi anemia (FA) is a hereditary DNA repair disorder characterized by progressive pancytopenia with bone marrow failure, variable congenital malformations and predisposition to develop hematological or solid tumors. "Among these 14 pathways, four major pathways were enriched: SNARE interactions involved in the vesicular transport (BET1 and STX6), leishmaniasis (FCGR1A, CYBB, and FOS), hematopoietic cell lineages (FCGR1A, ITGA3, MME, and CD5) and Fanconi anemia pathway (SLX4, ATR, and TELO2)." (PMID 37601105, 2023).
prostate carcinoma (1 paper, 2023). A carcinoma that arises from epithelial cells of the prostate gland. "Next, YIPF6 is significantly overexpressed in castration-resistant prostate cancer; however, in the same disease BET1’s lower expression is associated with early relapse." (PMID 36979661, 2023).
Uterine leiomyoma (1 paper, 2022). The presence of a leiomyoma of the uterus. "Bet1 Golgi vesicular membrane trafficking protein-like (BET1L) rs2280543 single nucleotide polymorphism (SNP) and diet have been independently associated with uterine leiomyoma (UL)." (PMID 35477381, 2022).
tumor (3 papers, 2021 to 2023). "Expression levels of ATP2A1 were negatively associated with monocytes and macrophages, and positively correlated with B-cell infiltration, while BET1 demonstrated positive correlations only with tumor infiltration by macrophages and Th1 cells in CHOL." (PMID 34831096, 2021). "However, we compared expression profiles between tumor grades and found that SNX15, ATP2A1, PDCD10, BET1, and HMGA2 expressions were significantly (all p < 0.05) associated with tumor stages." (PMID 34831096, 2021). "Suggestively, our results indicated that SNX15, ATP2A1, PDCD10, BET1, and HMGA2 could serve as a biomarker signature of tumor progression and metastasis in CHOL patients." (PMID 34831096, 2021).
infection (2 papers, 2022 to 2024). The state of being infected such as from the introduction of a foreign agent such as serum, vaccine, antigenic substance or organism. "A549 cells treated with siRNA directed against BET1 or USE1 or with negative control siRNA (siBET1, siUSE1, or siNC, respectively) were infected with rMuV/AcGFP at a multiplicity of infection (MOI) of 0.05." (PMID 36480520, 2022).
myopathies (2 papers, 2023). "Indeed, BET1 (SNARE protein involved in the docking process of ER-derived vesicles with the cis-Golgi membrane) was moreover increased in the muscle tissue of patients with BICD2-associated myopathy (p1, p3, and p5)." (PMID 37047781, 2023). "Human genetic studies have identified pathogenic variants in critical proteins in the vesicular trafficking pathway, resulting in myopathies in affected patients such as GOLGA2, BIDC2 and BET1." (PMID 37432316, 2023).
BET1 also shares sentences with these, for which no sentence is quoted: cancer (2 papers); cataract (1); cognitive decline (1); colon cancer (1); colorectal cancer (1); epilepsy syndrome (1); glioma (1); heart failure (1); leishmaniasis (1); metastatic prostate carcinoma (1); neurodegenerative disease (1); neurogenic muscular atrophy (1); neurological diseases (1); progressive muscular dystrophy (1).